ATRX (ATRX chromatin remodeler)
Diseases named in the same sentence as ATRX in open-access papers (continued):
Sharing a sentence is not in itself a finding about the gene and the disease.
tumor (continued). "Neither ATRX nor MGMT protein expression changed in 31 cases of recurrent tumours." (PMID 29026176, 2017). "In addition, we found that having an ATRX mutant tumor did not affect patient OS or PFS in any of the five groups (all P > 0.05)." (PMID 28851427, 2017). "In contrast to sporadic PanNETs, ATRX and DAXX alterations were only seen in 6 % of PanNETs from MEN1 syndrome patients (but also as late event) and in 0 % of microadenomas suggesting a less important role for these alterations in MEN1 syndrome tumor progression." (PMID 27267993, 2016). "While reduced expression or inactivation of other tumour suppressor genes, including PTEN, NF1, ATRX and DAXX, has been associated with specific GBM subtypes, we are not aware of any other wild type gene that behaves as a tumour suppressor in some GBM subtypes and as an oncogene in others." (PMID 27083054, 2016). "We next assessed whether the aberrant chromatin status of the Xi also translated into X-linked gene reactivation by assessing XIST together with HDAC8, ATRX, MAGEA6, and TBL1X expression on fresh tumor stamps (including those analyzed above) or tumor-tissue cryosections." (PMID 25653311, 2015). "In non-MNA tumours, it has been shown that telomere maintenance is frequently achieved either through (i) genomic rearrangements that place TERT under the control of strong enhancer elements or (ii) ALT, which is associated with ATRX alterations in 55–60% of all ALT-positive cases." (PMID 40713849, 2025). "In the absence of telomerase, tumours may exploit a telomerase-independent mechanism for the telomere elongation known as ALT (Alternative Length Telomerase) phenotype, which is associated with inactivating mutations in ATRX or DAXX genes." (PMID 34573966, 2021). "The tumor cells were immunohistochemically positive for GFAP, ATRX, and H3 K27me3, but negative for synaptophysin, IDH1 R132H, and H3 K27M." (PMID 39432011, 2025). "Whereas tumor cell nuclei are negative for ATRX and possibly surrounded by GFAP, the nuclei of astrocytes are positive for ATRX and also surrounded by GFAP." (PMID 38263411, 2024). "However, the established role of FANCA, SLX4, BRCA2, and ATRX in DNA repair pathways is unlikely to be coincidental, especially considering that we identified mutations in other DNA repair pathway genes, including ATR, which was mutated in two tumours in our study." (PMID 39766052, 2024). "Only one intrachromosomal telomeric insertion was detected in an ATRX altered case (data not shown), while TERRA expression was elevated in ATRX altered tumours, although was not statistically significant (Two-sided Student’s t-test p>0.05)." (PMID 38978571, 2024). "Molecularly, the tumor presented as IDH 1 R132H negative, ATRX was retained and H3 K27M was negative." (PMID 33905054, 2021). "Control mice not receiving human tumor cells showed no positive cells for human-specific antigens, IDH1, Ki67 or ATRX (data not shown)." (PMID 32698368, 2020). "Previous findings in tumor cells and cell lines have shown a correlation between ALT and absence of ATRX at the protein or gene level." (PMID 26001292, 2015). "Tumor cells were positive for Olig2, PS100 and ATRX, and negative for R132H-IDH1." (PMID 30857565, 2019). "To correlate GPR158 expression with clinically, diagnostically and biologically relevant tumour entities, we defined oligodendrogliomas (O, n = 83) as IDH mutant, 1p/19q co-deleted tumours, and astrocytomas (A, n = 138) as IDH mutant, ATRX mutant tumours with no 1p/19q codeletion." (PMID 29720725, 2018). "Additionally, none of the putative tumor-suppressor genes relevant to LGG, namely, ATRX, CIC, FUBP1, and NOTCH1, showed correlations with overall survival (data not shown)." (PMID 27852048, 2017).
tumor (continued). "Tumor cells were positive for IDH1(R132H) and negative for ATRX." (PMID 26817999, 2016). "However, the limitations of the used method in combination with a possible presence of heterogeneous MNA, where neoplastic cells with and without MNA co-exist within the tumour, do not allow further specification on whether MNA and the ATRX aberration are present in the same cell population." (PMID 40713849, 2025).
cancer (277 papers, 2009 to 2026). A tumor composed of atypical neoplastic, often pleomorphic cells that invade other tissues. "This helps to explain why ATRX loss is often observed in human cancers that use the ALT pathway for chromosomal end protection." (PMID 41481722, 2026). "One of the central genetic events underpinning ALT cancers is well-established: approximately 90% of ALT-positive cancers lose ATRX gene expression, usually due to nonsense truncating mutations." (PMID 39921567, 2025). "ATRX-loss is also seen frequently in ALT cancer cells contributing to telomeric chromatin changes and TERRA expression." (PMID 40624280, 2025). "Menin, DAXX, and ATRX are therefore key proteins involved in the maintenance of gene transcription, and therefore their loss of function is associated with many cancer types for example leukaemia, prostate cancer, gliomas, and sarcomas." (PMID 39579056, 2025). "Despite the near-universal loss of ATRX in ALT cancers, and capacity to suppress the ALT pathway upon re-expression in established ALT cell lines, isolated loss of the gene is insufficient to induce the ALT phenotype in most cellular systems." (PMID 39921567, 2025). "Although many poor-prognosis ALT cancers also harbor ATRX/DAXX mutations, their biological contexts differ substantially." (PMID 41148828, 2025). "ATRX (alpha-thalassemia mental retardation X-linked) is a tumor suppressor gene, frequently mutated in various types of cancer, which encodes a SWI/SNF-like chromatin remodeler." (PMID 39892705, 2025). "We then assessed the survival potential of ATRX-deficient LiSa-2 ALT cancer cells in clonogenic assays." (PMID 40125273, 2025). "It is well-recognized that ALT cancer cells harbour higher levels of R-loops and this is partially attributable to loss of ATRX." (PMID 39921567, 2025). "In this study, we identified a wider panel of ALT-positive cell lines, including carcinomas, and we estimated the incidence of ATRX-damaging mutations among them." (PMID 40725011, 2025). "A significant proportion of ALT-positive cancers have mutations in the ATRX gene, which encodes a multifunctional protein with roles in chromatin remodelling, genome stability and replication fork processivity." (PMID 39657822, 2024). "Recent advances in cancer genome sequencing have revealed somatic mutations in ATRX and DAXX, which seem to be prevalent and unique to ALT-positive malignancies." (PMID 39021990, 2024). "Approximately 90% of ALT cancers harbor mutations in ATRX or DAXX9–11, which deposit histone H3.3 in heterochromatic genomic regions, including telomeres." (PMID 36805596, 2023). "Because of the implications in cancer and therapy there is growing interest in ATRX, which is reported as a frequently mutated gene in cancer." (PMID 37629169, 2023). "Mutations of ATRX are frequent in cancers that immortalize through the ALT (Alternative lengthening of telomeres) pathway." (PMID 36805596, 2023). "Some ATRX/DAXX deficient ALT-positive cancers expressed telomere insertions and telomere variant repeats." (PMID 37046606, 2023). "This is very interesting as literature has also shown that reduced ATRX is associated with loss of H3K9me3 and telomere lengthening—a hallmark of many cancers." (PMID 36624117, 2023).
cancer (continued). "Though most cancer-associated ATRX/DAXX mutations are truncations, missense mutations are also observed and their significance is not well comprehended." (PMID 37107548, 2023). "Unlike constitutive mutations observed in ATR-X syndrome, somatic ATRX mutations found in cancers are usually truncating non-sense mutations that are expected to completely abrogate ATRX activity." (PMID 37107548, 2023). "Prior studies have linked alterations in the alpha thalassemia/mental retardation syndrome X-linked (ATRX) or death domain-associated protein (DAXX) genes with ALT in a subset of cancers." (PMID 35740680, 2022). "The overexpression of the PDGFR alpha subunit has been reported to correlate with ATRX mutations in cancer cells." (PMID 35406561, 2022). "To test the feasibility of ATR inhibition in the treatment of high-grade neoplasms, we evaluated NF1- and ATRX-deficient cancer cells." (PMID 35740680, 2022). "Apart from ATRX, few somatic SNVs with obvious relevance for cancer were detected by WES/WGS with an overall low mutational load, which is concordant with previous studies." (PMID 35859155, 2022). "WEE1 is a kinase involved in cell cycle regulation and the DNA damage response and was also identified as a synthetic lethal partner specific to ATRX deficiency in cancer." (PMID 36497337, 2022). "The tumor suppressor proteins DAXX and ATRX are frequently mutated in cancers with alternative lengthening of telomeres (ALT)." (PMID 36028493, 2022). "ALT cancers in which ATRX is mutated also retain lower rDNA content than ALT-negative cancers owing to defective histone H3.3 deposition and heterochromatin formation at rDNA repeats." (PMID 35774233, 2022). "In line with this, a recent study reports that one promising possibility for targeting ATRX-deficient cancers is the use of WEE1 inhibitors." (PMID 35406561, 2022). "The insights afforded by our studies in stem cells can be leveraged to develop new precision medicine approaches that target metabolic pathways to treat cancers with specific ATRX mutations." (PMID 35998910, 2022). "Dysregulation of the TERRA through the cell cycle was documented in ALT-positive cancer cells due to the loss of ATRX." (PMID 35982970, 2022). "ATRX mutation is strongly associated to ALT-positive cancers, as it can contribute to the recruitment of H3.3 histone which maintains the heterochromatic morphology of the genome at telomeres level." (PMID 36497228, 2022). "DAXX and ATRX are tumor suppressor proteins that form a histone H3.3 chaperone complex and are frequently mutated in cancers with the alternative lengthening of telomeres (ALT)." (PMID 36028493, 2022). "In ALT-dependent cancer cells, frequent occurrence of ATRX/DAXX mutations is accompanied by DNA hypomethylation in subtelomeric regions." (PMID 35982970, 2022). "Alternative Lengthening of Telomeres (ALT) is a telomere maintenance pathway utilised in 15% of cancers that have been associated with mutations in ATRX." (PMID 33972520, 2021). "ALT cancers are strongly associated with inactivating mutations in ATRX; yet loss of ATRX alone is insufficient to trigger ALT, suggesting that additional cooperating factors are involved." (PMID 33972520, 2021). "Such tumour suppressive functions of ATRX are relevant to its mutation/loss across many cancer types." (PMID 33664771, 2021). "Pan-cancer analysis has identified a T cell-poor, macrophage-rich, phenotype that is found in solid tumors and which correlates with ATRX mutations across malignancies and specimens." (PMID 34763709, 2021). "The clinical significance of KDM4B inactivation in other ATRX-mutated ALT cancers requires further studies." (PMID 33972520, 2021).
cancer (continued). "This strongly suggests that both H3.3G34R and IDH1R132H can inhibit KDM4B activity, and that inhibition of KDM4B is a common component in promoting ALT in ATRX-mutated cancers." (PMID 33972520, 2021). "One common and striking feature of ALT cancers is the remarkable prevalence of mutations in the ATRX–DAXX–H3.3 axis." (PMID 34828344, 2021). "Given that this induction was specific to these cell lines, it is likely that additional genetic or epigenetic events occur alongside ATRX loss to facilitate induction of ALT in human cancer." (PMID 34828344, 2021). "We excluded the sex-restricted tumors and cancer projects with ATRX mutation frequency less than 5%." (PMID 33678158, 2021). "It will be interesting to investigate if FH and SDHx mutations also inhibit KDM4B and act as cooperating factors to promote ALT in ATRX-mutated cancers." (PMID 33972520, 2021). "Our results suggest that in ATRX-mutated ALT cancers, loss of KDM4B results in an increase of H3K9me3- and HP1α-containing heterochromatin to a level that can sustain and stabilise the formation of APBs." (PMID 33972520, 2021). "Remarkably, half of cancer projects (50%, 17/34) showed significantly sex differences in ATRX mutation." (PMID 33678158, 2021). "Altogether, these analyses demonstrate that multiple recurrent mutations affecting young adult cancers (e.g., ATRX in both LGG and UCEC) were distinct from those affecting later-onset cases, and correlated with their subtype distributions." (PMID 34788626, 2021). "Cancer cells harboring ATRX mutations exhibit chromatin instability and impaired DNA damage response, making them vulnerable to DNA-damaging treatments." (PMID 34648115, 2021). "When assessing panels of ALT cancers, work has previously shown that over 90% of ALT cancers display undetectable levels of ATRX protein and mutations or deletions in the ATRX gene." (PMID 34828344, 2021). "Recently, studies have shown that ATRX is frequently mutated in cancers and its loss is intimately linked to the alternative lengthening of telomeres (ALT), a mechanism that contributes to cellular immortality in cancer." (PMID 32376827, 2020). "Loss of ATRX or DAXX though mutation has been reported in cancers which are histogenetically remote from OC." (PMID 32533344, 2020). "Sequencing of cancer genomes discovered that mutations of the ATRX/DAXX complex and the histone variant H3.3 are prevalent in ALT+ cancers." (PMID 32175073, 2020). "DAXX and/or ATRX expression has been associated with both better and worse survival in analysis of other cancers." (PMID 32533344, 2020). "Infection of co-cultured primary and ATRX-deficient cancer cells revealed that mutant HSV-1 selectively killed ATRX-deficient cells." (PMID 30745338, 2019). "Consistent with this, the frequency of mutation of proteins involved with H3.3 deposition, such as ATRX, appears to be much higher than that seen for chaperones for H3.1 and H3.2 in pediatric cancer (pecan.stjude.cloud/proteinpaint)." (PMID 31086012, 2019). "Due to the near universal loss of the SWI/SNF protein ATRX in ALT cancer, and the ability of ATRX to suppress markers of ALT in a DAXX dependent manner, it would appear that loss of ATRX is a key factor in the development of ALT." (PMID 32039009, 2019). "Genetically, ALT positive cancers frequently harbor inactivating mutations in the gene loci of α-thalassemia/mental retardation syndrome X-linked (ATRX), Death domain associated protein (DAXX), and H3 histone family member 3A (H3F3A/H3.3)." (PMID 30214690, 2018). "A striking correlation has been observed between ALT activity in various human cancers and loss of the ATP-dependent helicase ATRX or its binding partner, the H3.3-specific histone chaperone DAXX, both of which are constituents of PML bodies." (PMID 29848986, 2018). "In this way, we established compelling mechanistic links between ATRX deficiency and targetable molecular networks classically implicated in cancer cell motility." (PMID 29535300, 2018).